DNAI2 (dynein axonemal intermediate chain 2)
Description:
Component of dynein, a family of motor proteins essential for movement along microtubules (By similarity). Required for structural and functional integrity of cilia (By similarity). Part of the dynein complex of respiratory cilia.
Synonyms: CILD9; DIC2; oda6
Tractability: Small molecule: a structure with a bound ligand is known.
Gene: Protein-coding gene on chromosome 17 (74,274,234 to 74,314,886, forward strand). Ensembl gene ENSG00000171595.
Subcellular location: Cytoplasm, cytoskeleton, cilium axoneme; Dynein axonemal particle
Subcellular location (Human Protein Atlas): Connecting piece; Mid piece; Calyx
Gene Ontology:
Molecular function: microtubule motor activity; protein binding; dynein heavy chain binding; dynein light chain binding
Biological process: cilium assembly; cilium movement; determination of left/right symmetry; outer dynein arm assembly
Cellular component: axonemal dynein complex; axoneme; outer dynein arm; sperm flagellum; dynein axonemal particle; 9+2 motile cilium; cilium; cytoplasm; external side of plasma membrane
Genetic constraint (gnomAD): Loss-of-function variants: 58 observed, 74.75 expected, observed/expected ratio (o/e) 0.78, 90% interval 0.63 to 0.97. The upper end of that interval is the gene's LOEUF score, 0.97, which puts it in group 4 of 6, group 1 being the genes least tolerant of losing a copy. Missense variants: 683 observed, 837.07 expected, observed/expected ratio (o/e) 0.82, 90% interval 0.76 to 0.87. Synonymous variants: 288 observed, 329.05 expected, observed/expected ratio (o/e) 0.88, 90% interval 0.79 to 0.96.
Gene-disease validity (ClinGen):
ClinGen rates the evidence that DNAI2 causes each of these diseases.
primary ciliary dyskinesia 9 (autosomal recessive): Definitive.
Homologues: Orthologues: chimpanzee DNAI2 (99% identical), macaque DNAI2 (96% identical), dog DNAI2 (86% identical), rabbit DNAI2 (86% identical), pig DNAI2 (86% identical), guinea pig DNAI2 (85% identical), rat Dnai2 (85% identical), mouse Dnai2 (85% identical), zebrafish dnai2a (50% identical), Drosophila melanogaster mmm (23% identical). Paralogues in human: DNAI3 (21% identical), DNAI4 (18% identical), DYNC1I2 (17% identical), DNAI1 (17% identical), DYNC1I1 (17% identical), DYNC2I2 (16% identical), DYNC2I1 (14% identical).
Diseases named in the same sentence as DNAI2 in open-access papers:
DNAI2 is named in the same sentence as 16 diseases in open-access papers, as found by Europe PMC text mining. Sharing a sentence is not in itself a finding about the gene and the disease. The quoted sentences say what the papers report.
primary ciliary dyskinesia (4 papers, 2020 to 2025). A rare, genetically heterogeneous, primarily respiratory disorder characterized by chronic upper and lower respiratory tract disease. "•First reported case of a rare homozygous DNAI2 mutation in an 11-year-old Libyan boy from a non-consanguineous family suffering from primary ciliary dyskinesia (PCD)." (PMID 41018726, 2025). "Furthermore, the strongest interacted genes from our PPI data were primary ciliary dyskinesia-related genes DNAI1, DNAI2, and DNAH5, suggesting the role of cilia in CPAM." (PMID 37165378, 2023).
Huntington disease (2 papers, 2021 to 2022). Huntington disease (HD) is a rare neurodegenerative disorder of the central nervous system characterized by unwanted choreatic movements, behavioral and psychiatric disturbances and dementia. "The hub genes in gene set B were DNAI2, DNAI1, DNAH1, DNAH9 and DNALI1, all of which were enriched in Huntington’s disease." (PMID 36577966, 2022).
amyotrophic lateral sclerosis (1 paper, 2025). Amyotrophic lateral sclerosis (ALS) is a neurodegenerative disease characterized by progressive muscular paralysis reflecting degeneration of motor neurons in the primary motor cortex, corticospinal tracts, brainstem and spinal cord. "DNAH10 (Duroc) and DNAI2 (Landrace) are involved in the biological process of amyotrophic lateral sclerosis." (PMID 39943208, 2025).
Anxiety (1 paper, 2008). Intense feelings of nervousness, tension, or panic often arise in response to interpersonal stresses. "No individual effect of the four NSCS analysed was significant, however the interaction between GPR156 and DNAI2 was significantly associated (p = 0.04) with childhood depression/anxiety in this cohort." (PMID 18270580, 2008).
Hydrocephalus (1 paper, 2021). Hydrocephalus is an active distension of the ventricular system of the brain resulting from inadequate passage of CSF from its point of production within the cerebral ventricles to its point of absorption into the systemic circulation. "The occurrence of PCD and hydrocephalus has been reported in the past and has been shown to be associated with mutations in various genes (DNAI1, DNAH5, DNAH11, DNAI2, KTU, and RSPH9/4A)." (PMID 33999288, 2021). "They concluded that this report contributed to better delineation of the important role of DNAI2 as causative of PCD phenotype, suggesting that the variations in DNAI2 may be a new genetic risk factor for hydrocephalus." (PMID 33999288, 2021).
lung carcinoma (1 paper, 2024). "This is the first study to determine the role of PTEN-mediated DNAI2 expression in the hyperplasia of bronchial epithelial cells in EGFRL858R-induced lung cancer." (PMID 38499532, 2024).
situs inversus (1 paper, 2023). A congenital condition in which there is complete right-to-left reversal of the position of the major thoracic and abdominal organs (that is, they are arranged in a mirror image of the normal positioning). "A total of 36% of situs inversus cases in our study were associated with the following genes: DNAH5, DNAI1, DNAI2, DNAAF5, and LRRC56." (PMID 37892347, 2023).
Situs inversus totalis (1 paper, 2022). "Previous studies have shown truncated variants in DNAI2 result in randomization of left/right body asymmetry and develop situs inversus totalis due to altered motility of nodal cilia." (PMID 36303540, 2022).
DNAI2 also shares sentences with these, for which no sentence is quoted: asthma (1 paper); ciliopathies (1); genetic disease (1); Hepatic steatosis (1); infection (1); male infertility (1); tumor (1); Viral infection (1).